PKD1 (polycystin 1, transient receptor potential channel interacting)
Diseases named in the same sentence as PKD1 in open-access papers (continued):
Sharing a sentence is not in itself a finding about the gene and the disease.
hydrops (1 paper, 2010). "A functional knockout of PKD1, the gene encoding the polycystin 1 protein, resulted in an embryonic lethal phenotype in mice presenting with hydrops, cardiac conotruncal defects, and renal cystogenesis." (PMID 21052534, 2010).
hydrops fetalis (1 paper, 2017). Hydrops fetalis is a severe and challenging fetal condition usually defined as the excessive accumulation of fetal fluid within the fetal extravascular compartments and body cavities that manifests as edema, pleural and pericardial effusion and ascites. "Indeed, PC1 is highly expressed in both osteoblasts and osteocytes and a homozygous PKD1 null mutation in mice was shown to cause polyhydramnios, hydrops fetalis, spina bifida, and osteochondrodysplasia." (PMID 29326910, 2017).
Hypercalciuria (1 paper, 2024). "Although we did not observe frank hypercalciuria or hypermagnesiuria on any of the time points in iKsp‐Pkd1−/− mice, the similar urinary Mg2+ and Ca2+ excretion as control animals implies a renal leak, that is, the inability of the kidneys to increase reabsorption upon reduced serum levels." (PMID 38561249, 2024).
hyperuricemia (1 paper, 2020). An abnormally high level of uric acid. "The multivariate analysis that included age, eGFR, PKD1 mutation, urinary protein excretion, hyperuricemia, and serum phosphate showed that eGFR (HR, 0.82; 95% CI, 0.74–0.90; p < 0.001) and serum phosphate (HR, 6.78; 95% CI, 1.94–34.02; p = 0.002) were independently associated with RRT." (PMID 32178226, 2020).
hypopharyngeal tumors (1 paper, 2024). "High PKD1 protein levels were found to be markedly more prevalent in tissue samples derived from the oropharynx (26% vs. 7%), while low PKD1 protein levels were more frequent in hypopharyngeal tumors (24% vs. 11%)." (PMID 39408603, 2024).
intracerebral hemorrhage (1 paper, 2023). A cerebrovascular disorder characterized by bleeding into one or both cerebral hemispheres including the basal ganglia and the cerebral cortex. "Across subtypes, the highest hit rate (HR) was intracerebral hemorrhage (ICH, 7/18 = 38.9%), particularly with the etiological subtype of structural vasculopathy (4/4 = 100%, PVs in ENG, KRIT1, PKD1, RNF213); followed by ischemic small vessel disease (SVD, 15/48 = 31.3%; PVs in NOTCH3, HTRA1, HBB)." (PMID 36580209, 2023).
laryngeal tumors (1 paper, 2024). "Tissue samples from laryngeal tumors showed a rather even balance between low and high PKD1 expression (15% vs. 17%, respectively)." (PMID 39408603, 2024).
leukodystrophy (1 paper, 2025). Leukodystrophies are a group of rare, progressive, metabolic, genetic diseases that affect the brain, spinal cord and often the peripheral nerves. "Of note, one patient with a PKD1 variant was affected also by GJC2 leukodystrophy." (PMID 39384646, 2025).
lung neoplasm (1 paper, 2020). A benign or malignant, primary or metastatic neoplasm involving the lungs. "Similarly, the impact of PKD1 in lung neoplasms is unclear due to the paucity of studies and often contradictory results." (PMID 33138224, 2020).
memory impairment (1 paper, 2018). "Altogether, these findings provide direct evidence that PKD1-mediated signaling may play a critical role in the induction of learning and memory impairments by DHPG infusion into the hippocampal CA1 area." (PMID 29614089, 2018).
metastatic melanoma (1 paper, 2017). A melanoma that has spread from its primary site to another anatomic site. "In conclusion, our study suggests, for the first time, that while cPKCs don’t embody a pertinent therapeutic target, inhibition of PKD1 represents a novel attractive approach for the treatment of metastatic melanoma." (PMID 28056869, 2017). "Interestingly, PKD1 knockdown also induced the expression of E-cadherin in M4T2 metastatic melanoma cells." (PMID 28056869, 2017). "Next, to allow direct analysis of the role of PKD1 inhibition in human metastatic melanoma, M2 cell clones stably expressing shRNAs directed against PKD1 (named P2, P3, P4, P5, P6 and P7) or scrambled shRNA control (named C1 and C2) were generated by lentiviral particles transduction." (PMID 28056869, 2017).
mitral valve regurgitation (1 paper, 2023). "Mutations in PKD1 are associated with mitral valve regurgitation in humans." (PMID 36639367, 2023).
mucinous tumors (1 paper, 2023). "Although non-mucinous tumors predominated in both cohorts, a significantly higher percentage PKD1-mutated tumors were likely to be mucinous than were PKD1 wild-type tumors." (PMID 37542051, 2023).
nephrolithiasis (1 paper, 2019). The presence of a calculus in the pelvis of the kidney; this is most often composed of mineral salts and proteins. "In summary, the presented case is the first reported pediatric case with dual mutation (PKD1 and GANAB) and nephrolithiasis." (PMID 30792735, 2019). "This case is the first case of combine presentation on PKD1 and PKD3 in a pediatric patient with nephrolithiasis." (PMID 30792735, 2019).
nephromegaly (1 paper, 2024). "Moreover, given the large deletion from exon 2 to exon 34, with PKD1 consisting of 46 exons, and particularly considering the typical phenotype with nephromegaly and rapidly progressive CKD, we may classify the variant as likely pathogenic." (PMID 39858586, 2024).
oligohydramnios (1 paper, 2020). A lower than normal quantity of amniotic fluid in the amniotic sac as compared to normal values. "In this study, a heterozygous missense mutation (PKD1: c.6571C > T) in a fetus with bilateral echogenic kidneys and two frame shift deletions (PKHD1:c.8301del and c.4481del) in a fetus with bilateral hyperechogenic and enlarged kidneys combined with oligohydramnios were identified." (PMID 32779812, 2020).
oral squamous cell carcinoma (1 paper, 2022). "Higher expression of PKD1 correlated with poor differentiation in oral squamous cell carcinoma." (PMID 35707371, 2022).
pericardial effusion (1 paper, 2022). Fluid collection within the pericardial sac, usually due to inflammation. "Pericardial effusion was observed in subjects with PKD1 and PKD2 mutations." (PMID 35207400, 2022). "Among two subjects who had both PKD1 and PKD2 mutations, one had pericardial effusion > 5 mm." (PMID 35207400, 2022).
Pleural effusion (1 paper, 2022). The presence of an excessive amount of fluid in the pleural cavity. "Pathogenic CNV in 16p13.3 (33.98 kb deletion) altered TSC2 and PKD1 genes that were postulated to contribute to driving ascites and pleural effusion." (PMID 34980134, 2022).
Polyhydramnios (1 paper, 2010). The presence of excess amniotic fluid in the uterus during pregnancy. "At later time points, the polyhydramnios became more severe and abnormalities in Pkd1−/− placentas became progressively more noticeable." (PMID 20862291, 2010). "Selective inactivation of Pkd1 and Pkd2 in endothelial cells resulted in polyhydramnios and abnormalities similar to those observed in Pkd1−/− placentas." (PMID 20862291, 2010).
secondary hypertension (1 paper, 2023). High blood pressure caused by an underlying medical condition. "Rare variation of the SSTR2, ATOH1, and PKD1 genes were associated with secondary hypertension." (PMID 37059828, 2023).
Stillbirth (1 paper, 2022). Death of the fetus in utero after at least 22 weeks of gestation. "After transferring the 227 SCNT embryos into two recipient gilts, five heterozygous PKD1 mutant cloned piglets were obtained, including one stillbirth." (PMID 34980882, 2022).
subarachnoid hemorrhage (1 paper, 2023). A serious neurological disorder characterized by intracranial hemorrhage into the subarachnoid space. "WES detected an intronic pathogenic variant PKD1 c.11014-10C > A in a 38-year-old man who suffered from subarachnoid hemorrhage by a ruptured anterior communicating artery aneurysm and PKD." (PMID 36580209, 2023).
thyroid cancer (1 paper, 2023). "Two of these kinases, PKC (theta) and PKD1, have been previously reported to be prognostic in thyroid cancer and might represent new targets for treatment." (PMID 37760447, 2023). "Conversely, mutations in higher-ranked kinases such as CHK2 (rank 15) or PKD1 (rank 18) are rare (less than 1% of the PTC cases) and do not seem to contribute to thyroid cancer." (PMID 37760447, 2023).
urolithiasis (1 paper, 2022). Stone(s) within the urinary tract. "The third variant, c.5528G > T (p.Gly1843Val), in exon 15 PKD1, was a heterozygous uncertain significance missense variant, identified in a 33-year-old male, with urolithiasis, kidney enlargement, multiple cysts in both kidneys and HTN phenotype." (PMID 37543885, 2022).
viral infection (1 paper, 2017). "Thus, the overexpression of the wt or PKD1 mutants in the context of viral infection has a profound effect, reducing viral replication." (PMID 28228588, 2017).
kidney disease (81 papers, 2007 to 2026). "There is a clear genetic basis for ADPKD, a heterogeneous disorder resulting from gene mutations in the polycystic kidney disease 1 gene (PKD1) or polycystic kidney disease 2 gene (PKD2)." (PMID 41181723, 2025). "ADPKD is the prevailing inherited renal disorder resulting from mutations in PKD1 (encoding polycystin-1) or PKD2 (encoding polycystin-2), which mainly presents with cysts of varying sizes in the kidneys bilaterally." (PMID 39975561, 2025). "Mutations in the PKD1 gene account for approximately 78-85% of patients and cause more severe forms of nephropathy than mutations in the PKD2 gene do." (PMID 41181723, 2025). "ADPKD is the most common monogenic kidney disease and an important cause of end-stage kidney disease, caused by mutations in the PKD1 or PKD2 genes in the majority of the cases, leading to dysfunction of their encoded proteins, PC-1 and PC-2." (PMID 40980664, 2025). "We identified rare pathogenic variants in known monogenic kidney disease genes, including PKD1 and COL4A4, confirming their role in disease susceptibility." (PMID 40770708, 2025). "Previous research demonstrated that the position of the PKD1 gene mutation correlates with renal disease severity." (PMID 39457385, 2024). "It has been shown that lysosomal and autophagy defects caused by calpain-induced lysosomal membrane permeabilization (LMP) are closely associated with the loss of the polycystic kidney disease gene 1 (PKD1) in kidney disease." (PMID 36703913, 2023). "With an estimated incidence of 1:1000 to 1:400 individuals, ADPKD is the most common single-gene inherited kidney disease primarily caused by pathogenic mutations in PKD1 and PKD2 genes, encoding polycystin-1 and polycystin-2, respectively." (PMID 37667185, 2023). "The polycystic kidney disease 1 (PKD1) gene encodes the membrane bound protein polycystin 1, which is a C-type lectin and has multiple cell recognition domains, and thus the binding of B. bifidum to this molecule seems plausible." (PMID 35768415, 2022). "Genotype-phenotype correlations in ADPKD show more rapid progression of kidney disease in patients with PKD1 variants and especially in those patients carrying variants resulting in protein truncation." (PMID 34676227, 2021). "For example, mutations in PKD1 are more prevalent and lead to more severe kidney disease when compared with PKD2 mutations." (PMID 33869988, 2021). "Variants in PKHD1 are the main cause of ARPKD with phenotypical overlay e.g., of kidney disease in patients with other underlying genetic changes, including biallelic hypomorphic PKD1 variants." (PMID 34676227, 2021). "These include polycystic kidney disease-associated proteins (Pkd1, Pkd2), calcium/calmodulin-dependent protein kinases (Camk genes), and Regucalcin, but not randomly selected genes." (PMID 32457326, 2020). "Polycystic kidney disease 1 (Pkd1) and Pkd2 genes encoding for polycystin-1 (PC-1) and polycystin-2 (PC-2) form a mechanosensory complex in the primary cilia of kidney and vascular endothelial cells." (PMID 29057897, 2017). "Very recently, in a genomic mutation heterozygous for polysystic kidney disease 1 (Pkd1), the deletion is restored by spontaneous mitotic recombination." (PMID 22969812, 2012). "Genetic testing with a 385-gene NGS-based kidney disease panel (the Renasight test) identified heterozygous truncating pathogenic variants in PKD1: c.3957_3994dup p.(Asp1332Glyfs*27)) (ClinVar ID VCV003376509.1) and PRKCSH: c.374_375del p.(Glu125fs)) (ClinVarID VCV001048653.34)." (PMID 41659942, 2026). "Our results suggest that genetic modifiers that affect the onset of this renal disease may be present in some families, such as the co-inheritance of a weak allele of PKD1 or PKD2 or a variant in a cis position concerning the major variant." (PMID 38541974, 2024).
kidney disease (continued). "From the genotype aspect, ADPKD-associated PKD1 mutations were mainly monoallelic, and majority of the mutations were destructive, implying that monoallelic mutations with haploinsufficiency of PKD1 potentially caused kidney disease." (PMID 35620448, 2022). "Prior studies have shown that mutations in PKD1 correlate with various renal diseases; therefore, mutations in PKD1 might reduce miR-4516 expression." (PMID 32727098, 2020). "Recent studies have delineated a strong genotype-phenotype correlation with the most severe kidney disease associated with PKD1 protein-truncating mutations, intermediate disease severity associated with PKD1 non-truncating mutations, and mild disease associated with PKD2 mutations." (PMID 31358787, 2019). "Such development tubular defects may be caused by an abnormal glycosylation of polycystin-1 (PC-1), a responsible gene product of polycystic kidney disease 1 (PKD1) for human autosomal polycystic kidney disease." (PMID 27258268, 2016). "The uniqueness of the molecular phenotype of the microvasculature observed in ADPKD compared to kidney diseases, and parallel findings in Pkd1RC/RC mice, could be driven by intrinsic consequences of a PKD1 pathogenic variant or deletion on endothelial development and function." (PMID 40114603, 2025). "In addition, several important renal disease-causing genes such as the major genes for ADPKD (PKD1) and aHUS (CFH and its related CFHR genes) are located in the most genomically complex regions that require a specific targeted design in order to not miss any disease-causing variant in these genes." (PMID 33712733, 2021). "Patients with PKD1 mutations present with more aggressive kidney disease than those with PKD2 mutations, so renal replacement therapy is performed at a younger age in patients with PKD1 gene mutations." (PMID 36422264, 2022). "Nevertheless, some PKD1/TSC2-CGS patients have milder renal disease with mosaicism being the main reason which is rather common in these cases but not supported by the blood derived DNA studies here." (PMID 26077033, 2015). "Genetic inactivation of Kcnn4 markedly improves kidney disease in an adult Pkd1 mouse model." (PMID 41122971, 2025). "This protein, besides its well-known role in kidney disease, is implicated in the structural integrity of blood vessels with a potential role in SCAD pathogenesis: VUS in PKD1 were found in heterozygous form in 14% of our patients, without any kidney involvement." (PMID 39654947, 2024). "However, the penetrance of kidney disease is known to vary according to a specific gene (e.g., PKD2 vs. PKD1) or a specific mutation type (e.g., missense vs. truncating variants)." (PMID 38097619, 2023). "Next, we determined if suramin could reduce renal inflammation in Pkd1-miR Tg mice as has been shown in other kidney disease models." (PMID 35955634, 2022). "Mutations in PKD1 or 2 were described almost exclusively in patients with congenital or cystic disease; COL4A–either 3, 4 or 5- were prevalently found in renal diseases defined as “glomerular”, while UMOD mutations were found in patients with a more heterogeneous renal phenotype." (PMID 35207681, 2022). "Even among PKD1 mutants, truncating mutations were associated with more severe renal disease than non-truncating mutations." (PMID 35629189, 2022). "ADPKD is the most common inherited renal disease, which is caused by mutations of PKD1 (encoding polycystin-1) or PKD2 (encoding polycystin-2) and is characterized by multiple cysts in the kidneys which enlarge over time and lead to end-stage renal disease failure." (PMID 35050181, 2022). "While the PKD1 and PKD2 mutations are prevalent across all ethnic groups, there are some genetic variants more common in African American populations that may influence kidney disease progression." (PMID 39457385, 2024). "Moreover, gene-set enrichment analyses suggest the relationship might extend beyond PKD1 to other renal disease genes." (PMID 33125268, 2020).
kidney disease (continued). "In addition to the FBN1 gene, we also found that 27 patients had mutations in the PKD1 gene, however these patients did not have kidney disease, and 16 of the 27 patients expressed aortic related complications." (PMID 33200202, 2020). "Five genes (PKD1, PKD2, and COL4A3/A4/A5) accounted for the majority of diagnoses in both our cohort and others, suggesting that focusing on these common genes can capture most hereditary kidney disease cases." (PMID 40533884, 2026). "However, we performed whole gene sequencing of the PKD1 gene for family members, including affected son, and his mildly affected father, who showed no clinical manifestation of kidney disease." (PMID 24842140, 2014).